MIR6724-2 (microRNA 6724-2)
Synonyms: hsa-mir-6724-2
Gene: MicroRNA gene on chromosome 21 (8,249,505 to 8,249,596, forward strand). Ensembl gene ENSG00000274060.
Homologues: Paralogues in human: MIR6724-1 (100% identical), MIR6724-3 (100% identical), MIR6724-4 (100% identical).